C5AR1 (complement C5a receptor 1)
Diseases named in the same sentence as C5AR1 in open-access papers (continued):
Sharing a sentence is not in itself a finding about the gene and the disease.
tumor (continued). "Because we had observed stromal C5aR1 expression in irradiated tumors, we next investigated immune infiltration changes in tumor draining lymph nodes and tumors following PMX205 and RT." (PMID 37824211, 2023). "It has been shown that macrophages can secrete C5a under stress conditions 17, leading to myeloid-derived suppressor cells (MDSCs) infiltration into the tumor microenvironment (TME) via its receptor C5aR1, which results in TME suppression." (PMID 37064877, 2023). "The results revealed that CD4+ and CD8+ T cells in GC tissues with high (+++) C5aR1 levels were particularly clustered in the peripheral tumor stroma, with a small proportion of immune cells infiltrating the stroma of the parenchyma of tumor mass." (PMID 36508191, 2023). "Altogether, these results suggest that the C5aR1 gene is related to the immune system that plays a key role in the inflammatory and tumor immune responses, promoting the carcinogenesis and progression of GC." (PMID 36508191, 2023). "Through an integrated screening approach, we identified complement receptor C5aR1 as a druggable target, which inhibited radiation-induced cell death/apoptosis through regulation of tumor cell fate." (PMID 37824211, 2023). "Among these genes, C5aR1 expression was transiently induced following radiotherapy, likely as a stress response mounted to promote tumor cell survival." (PMID 37824211, 2023). "This is important because recent reports indicate that C5aR1 intracellular pools are present in tumor cells where they contribute to tumorigenesis through β-catenin stabilization." (PMID 37824211, 2023). "In contrast, the inhibition of C3aR and C5aR1 accelerated tumor growth in a mouse orthotopic head and neck squamous cell carcinoma model." (PMID 35860237, 2022). "C5AR1 signaling also contributes to the promotion of tumor growth by suppressing the adaptive immune response against tumor antigens and recruits myeloid-derived suppressor cells (MDSCs) into tumor cells." (PMID 36323738, 2022). "We combined adjuvant chemotherapy treatment with complement receptor antagonists (SB290157 blocking C3aR, or PMX53 blocking C5aR1) following primary tumor resection." (PMID 36184683, 2022). "Together, the synergic effects of the hub genes, CCL19, CXCL12, and C5AR1, promote chemotaxis, tumour proliferation, and even metastasis, which are in line with previous studies and evidenced by the progressive MCTVT growth." (PMID 34980125, 2022). "C3a and C5a acting through their cognate receptors C3aR, C5aR1 and C5aR2, respectively, are central mediators of tumor promoting responses in the tumor microenvironment." (PMID 35860237, 2022). "In glioblastoma, C5aR1 inhibitors in combination with temozolomide promote induced DNA damage and tumor cell apoptosis, thereby increasing sensitivity to chemotherapy." (PMID 36294966, 2022). "C5ar1−/− mice also showed a mild increase in tumor number (P = 0.0048) and tumor onset time (P = 0.0031), whereas these parameters were unaltered in C5ar2−/− mice." (PMID 32682912, 2021). "After confirming the KO effect, we found that C5aR1+ neutrophil-cultured tumor cells (MCF-7C5RN and MDA-MB-231C5RN) exhibited an increase of glucose uptake, lactate secretion, and ATP production than the control group." (PMID 34312368, 2021). "Collectively, we identify a specific neutrophil subpopulation, C5aR1+ neutrophils, that correlates with tumor progression and poor survival of BC patients." (PMID 34312368, 2021). "Among the 32 tumour entities investigated in the present study, 19 were evaluated for C5aR1 expression for the first time." (PMID 33606748, 2021). "Here, by analyzing BC single-cell RNA-seq data, we found that C5aR1 was highly expressed in tumor-infiltrating neutrophils relative to that from normal tissues and blood." (PMID 34312368, 2021). "Experimental studies showed that the use of C5aR1 inhibitors led to reduced tumor growth in different tumor mouse models." (PMID 34572075, 2021).
tumor (continued). "In this study, by investigating the single-cell RNA sequencing data, we identify a new neutrophil subset, C5aR1-positive neutrophils, that correlates with tumor progression and poor survival for BC patients." (PMID 34312368, 2021). "Overall, significant C5aR1 expression was observed in the majority of the 32 tumour entities investigated." (PMID 33606748, 2021). "Although accumulating evidence agrees on the pro-tumoral role of C5, C3, C3AR1, and C5AR1, the immune infiltration is largely controlled by the properties of the tumor cells themselves." (PMID 34439277, 2021). "Unexpectedly, the tumor area was increased in C5ar1−/− (P < 0.0001) and C5ar2−/− (P = 0.0001) mice compared with WT controls." (PMID 32682912, 2021). "Apart from its role as immune modulators, C5aR1 expression in tumor cells is involved in the activation of various signals that promote cancer development." (PMID 34312368, 2021). "Analysis of differential gene expression at different tumor stages revealed an association between tumor stages and high gene expression of C3 in THCA and KIRC; C3AR1 in SKCM; and C5AR1 in BLCA, THCA, and SKCM." (PMID 34439277, 2021). "This fully human anti-C5aR1 antibody is being developed in advanced solid tumors, in which C5aR1 activity is suggested to suppress T cell and natural killer (NK) cell activity in tumor immune surveillance." (PMID 33362783, 2020). "C5aR1 seems to have pro-tumoral role, whereas C5aR2 has more limited impact but tends to modulate the tumor growth." (PMID 33113844, 2020). "Polymer nanoparticles that are able to activate the complement system were found to increase tumor growth in a C5aR1-dependent manner, presumably through the liberation of C5a and the recruitment and activation of proinflammatory macrophages and Tregs." (PMID 33488603, 2020). "(B) Each cell is colored according to expression value of the genes RPS19 and C5AR1 in tumor and non-tumor cells, respectively." (PMID 33155039, 2020). "The recognition of the anaphylatoxins by their receptors (C3aR, C5aR1 and C5aR2) present at the surface of some tumor cells leads to the activation of the signaling pathways PI3K, Erk 1/2 and AKT." (PMID 33113844, 2020). "In fact, C5aR1-dependent regulations of MDSC led to the suppression of antitumor CD8+T cells because depletion of these cells by anti-CD8 neutralizing antibody erased beneficial effects of C5aR1 blockade on tumor growth in a mouse model of HPV-induced cancer." (PMID 33488603, 2020). "Accordingly, pharmacological blockade of C5aR1 decreases the frequency of MDSCs and impairs tumor growth." (PMID 31031765, 2019). "It was further suggested that RPS19 immunosuppressive role in cancer involved its interaction with the complement receptor C5aR1 (CD88), promoting tumor growth in a transgenic model of breast cancer." (PMID 31506518, 2019). "C5aR1 inhibition also downregulates the expression of immunosuppression-related genes within the tumor milieu." (PMID 31031765, 2019). "It is well established that complement components and their receptors C3aR and C5aR1 are expressed in not only myeloid and tumor cells but also CD4+ T lymphocytes." (PMID 31379815, 2019). "C5 and its receptor C5aR1 expression was verified at protein level by immunohistochemistry on an independent ESFT tumour tissue microarray." (PMID 22084725, 2011). "C5aR1 is predominantly expressed by tumor-associated macrophages, and citalopram treatment enhances local macrophage phagocytosis and elicits CD8+ T anti-tumor immunity." (PMID 41661166, 2026). "The C5aR1 has emerged as a new class of immune checkpoint receptor in tumor immunotherapy." (PMID 41373839, 2025). "Furthermore, it has also been reported that the C5a–C5aR1 axis promotes the proliferation and metastasis of tumor cells by reducing the apoptosis of neutrophils and promoting an immunosuppressive microenvironment." (PMID 39736396, 2025). "C5aR1 expression was observed on the surface of cSCC tumor cells in vivo." (PMID 40056975, 2025).
tumor (continued). "We hypothesised that ER stress may induce C5aR1 expression in tumour cells and found that C5aR1 mRNA levels were increased in the presence of two different UPR inducers, tunicamycin and thapsigargin." (PMID 40695778, 2025). "In mouse models, silencing C5aR1 suppressed tumor growth and lung metastasis." (PMID 41300283, 2025). "In conclusion, our findings suggested that the C5a-C5aR1 axis may exert a tumour-promoting effect on the immune TME of PDAC." (PMID 41044172, 2025). "In the context of squamous cell carcinoma, C5a has been demonstrated to facilitate the pro-tumor characteristics of C5aR1+ mast cells and macrophages, whilst simultaneously inhibiting CD8+ T cell cytotoxicity and limiting chemotherapy-induced T cell responses, supporting the growth of tumors." (PMID 39958348, 2025). "Moreover, increased C5aR1 staining on the tumor cell surface was evident in mcSCC and cSCC metastases compared with non-mcSCC." (PMID 40056975, 2025). "Notably, inhibiting C5aR1 with PMX53 suppressed tumor growth, enhanced anti-tumor pathways, and improved PD-1 therapy efficacy." (PMID 41300283, 2025). "Finally, we tested the effects of pharmacologically targeting C5aR1 in a tumour spheroid model containing hypoxic regions." (PMID 40695778, 2025). "In addition, more abundant C5aR1 staining was observed on the tumor cell surface in RDEBSCC compared with normal skin." (PMID 40056975, 2025). "Additionally, the C5aR1 inhibition combined with GnP therapy facilitated tumour regression, and enhanced the antitumour immunity by adding ICB treatment in the immune TME of PDAC in vivo." (PMID 41044172, 2025). "This apparent discrepancy likely reflects the transient nature of tumor suppression by W54011, where early inhibition of C5aR1 may reduce initial tumor growth but fail to fully counteract sustained tumor-promoting cues from co-implanted tMSLCs." (PMID 41353504, 2025). "In addition, C5aR1 staining on the tumor cell surface and in TME fibroblasts was increased in mcSCC and cSCC metastases compared with non-mcSCC." (PMID 40056975, 2025). "The multifaceted roles of C5a-C5aR1 in tumor immunity include: First, direct cytotoxic effects." (PMID 41373839, 2025). "Moreover, our studies suggest that inhibition of C5aR1 as a strategy to deplete pro-tumor macrophage function to sensitize tumors to PARPi as well as with a broader range of therapeutic agents warrants exploration in the clinic." (PMID 38802355, 2024). "C5aR1 is expressed in a variety of cells, including myeloid-derived cells (such as macrophages, neutrophils, and monocyte subpopulations), specific lymphocytes, and tumor cells." (PMID 39368999, 2024). "Mice treated with C3aR1 (SB290157) and C5aR1 (PMX53) inhibitors had reduced tumor growth." (PMID 38339243, 2024). "Our data supports the contention that blocking C5aR1 would target pro-tumor macrophages while sparing pro-inflammatory function of macrophages suggesting that targeting C5aR1 could benefit patients receiving PARPi and potentially other therapies." (PMID 38802355, 2024). "The association of C5aR1 and MEF2C expression with the expression of a number of other TFs suggests that they may also contribute to the regulation of pro-tumor macrophage function potentially through C5aR1." (PMID 38802355, 2024). "Furthermore, we inferred the important interaction between tumor and stromal regions mediated by gene pair of C5AR1 and RPS19, which played roles of ligand and receptor, respectively." (PMID 38729966, 2024). "In contrast, pharmacological inhibition of C5aR1 signaling by its antagonist PMX-205 or deletion of C5aR1 is sufficient to attenuate the immunosuppressive microenvironment, suppress tumor growth, and reduce lung metastases, highlighting the potential value of targeting C5aR1 for CRC treatment." (PMID 38331868, 2024).
tumor (continued). "In addition, anti-C5aR1 Ab reduced PFKM ubiquitination in peritoneal macrophages from tumor-bearing mice, suggesting that upon C5aR1 inhibition or C5aR1 deletion, PFKM stabilization mediated by AKT2 activation was required for the M1 phenotype." (PMID 38331868, 2024). "Timing of drug administration, by blocking MEK to increase C5aR1 expression on immune-cell surfaces and then inhibiting C5aR might improve overall tumor response." (PMID 38458648, 2024). "To directly assess whether radiation could impact tumor cell–intrinsic expression of C5aR1 or C5, we turned to an in vitro system." (PMID 37824211, 2023). "Previous studies have reported that the relationship between C5aR1 expression and tumor immune infiltration may enhance tumor immune escape through a dysfunctional T cell phenotype." (PMID 36508191, 2023). "While C5aR1 is well-known for its role in the immune compartment, we found that C5aR1 is also robustly expressed on malignant epithelial cells, highlighting potential tumor cell–specific functions." (PMID 37824211, 2023). "The up-regulation of C5aR1 expression is closely related to tumor growth and metastasis." (PMID 36192575, 2023). "The defect in tumor uptake displayed by C5aR1–/– mice complicates the investigation of radiation responses in this model and might have contributed to some of the previous conflicting reports." (PMID 37824211, 2023). "In addition, a comparison of C5aR1 mRNA expression in 32 pairs of tumors and adjoining normal tissues in the database of TCGA revealed that its expression level was elevated in tumor tissues compared to adjoining normal tissues (P < 0.05)." (PMID 36508191, 2023). "Studies have shown that C5AR1 inhibitors could impair tumorigenesis and tumor metastasis, resulting in good clinical outcomes." (PMID 36497433, 2022). "We found that the mRNA expression of C1QA, C1QB, C1QC, C5AR1, C3AR1, C1QR (CD93), CR1, CR2, CR3 (ITGAM), and CR4 (ITGAX) were positively associated with almost all kinds of tumor immune cells, including CD8+ T cells, CD4+ T cells, B cells, macrophages, monocytes and DCs." (PMID 34813686, 2022). "In the present study, 32 different tumour entities were evaluated for C5aR1 expression." (PMID 33606748, 2021). "C5aR1 expression has also been described in a number of tumours." (PMID 33606748, 2021). "Presence of C5aR1 in the tumour cells of different tumour entities." (PMID 33606748, 2021). "Increased expression of C5AR1 correlates with tumor stage and tumor cell invasion of liver capsule." (PMID 33672651, 2021). "Here, as well as in other strongly C5aR1-positive tumour entities, C5aR1 may serve as an interesting target for future therapies." (PMID 33606748, 2021). "In addition to confirming published findings, we found noticeable C5aR1 expression in many tumour entities for the first time." (PMID 33606748, 2021). "Further, our correlation analysis suggests that these associations between the expression levels of C3, C3AR1, and C5AR1 and tumor immune infiltration could possibly enhance tumor immune evasion via dysfunctional T-cell phenotypes." (PMID 34439277, 2021). "Notably, C5aR1 expression in the different tumour entities displayed substantial inter-individual variability." (PMID 33606748, 2021). "In the majority of tumour types, a high percentage of cases showed significant C5aR1 expression." (PMID 33606748, 2021). "Intriguingly, the deficiency of C3aR1, C5aR1, or C5aR2 generated opposite results to the deficiency of C3, with a modest increase in tumor number and growth, whereas the MAC did not play a key role either way." (PMID 32682912, 2021). "This is especially exciting, as C5aR1 blockade can be combined with currently used immunotherapies such as Listeria monocytogenes-based vaccines, which aim to stimulate T cell responses to tumour and metastatic vasculature formation." (PMID 33659922, 2021).
tumor (continued). "In particular, the expression of the anaphylatoxin receptors C3aR and C5aR1 increased tumor progression and thus they could be targeted for anti-tumorigenic therapy." (PMID 34572075, 2021). "However, C5AR1 expression shows a weak (r = 0.2~<0.5) to poor (r < 0.2) correlation with tumor infiltrations of CD4+ T cells, CD4+ T cells, and B cells in various cancer types." (PMID 34439277, 2021). "This hypothesis was supported by flow cytometric analysis of tumor infiltrating leukocyte populations, which demonstrated a significant increase in T lymphocytes in mice treated with the C3aR/C5aR1 agonist." (PMID 33430104, 2021). "C5aR1 and C5aR2 seem to have opposite effects, especially in the tumor context." (PMID 33113844, 2020). "Given the proangiogenic functions of MDSC, it is surprising that only a few reports have linked complement to tumor angiogenesis, and in fact, none of them have demonstrated contribution of C5aR1 signaling in these cells to angiogenesis in primary sites." (PMID 33271774, 2020). "In addition, C3, CR4, and C5aR1 expression was positively related to the tumor purity and infiltration levels of multiple immune cells in stomach adenocarcinoma (STAD)." (PMID 33614473, 2020). "Ribosomal protein S19 (RPS19), upon release from dying tumor cells, interacts with C5aR1 expressed on MDSCs, promoting its recruitment to tumors, the generation of Tregs, the production of immunosuppressive cytokines (including TGF-β), and the reduction of CD8+ T-cell tumor infiltration." (PMID 31031765, 2019). "Indeed, lung primary tumors that metastasize to bone show higher C5aR1 levels than those that metastasize to other locations, suggesting its major role in the tumor-induced skeletal lesions." (PMID 31001273, 2019). "Interestingly, C5aR1 expression was detected in stromal fibroblasts located near the tumor." (PMID 40056975, 2025). "The C5a-C5aR1 axis may exert a tumour-promoting effect on the TME in PDAC." (PMID 41044172, 2025). "Additionally, C5a/C5aR1 not only promotes the formation of a tumor immunosuppressive microenvironment, but also participates in tumor angiogenesis and activates tumorigenic pathways within tumor cells." (PMID 41373839, 2025). "As tumour hypoxia is a key feature of the TME in solid tumours and is strongly associated with immunosuppression, we investigated the possibility that the dysregulation of C5aR1 may be caused by hypoxia-induced stress." (PMID 40695778, 2025). "We next tested whether MEK inhibition alters cell surface expression of C5aR1 in tumor macrophages." (PMID 38458648, 2024). "Moreover, the anti-tumor ability of anti-C5aR1 Ab was diminished in the presence of TH1020 in vivo." (PMID 38331868, 2024). "Interestingly, in AKPT tumor models, C5aR1 was expressed by both the tumor epithelium and stroma." (PMID 37824211, 2023). "Our results show that C5AR1 is specially expressed in TAMs and its expression is correlated with the M2-polarization score, indicating C5AR1+ TAMs may be potential targets for alleviating the immunosuppressive microenvironment and further improving the anti-tumor ability of immune cells." (PMID 38002057, 2023). "Furthermore, high expression levels of C3, C5, C3AR1, and C5AR1 are significantly (p < 0.05) associated with tumor subtypes in KIRC, LUAD, LUSC, and STAD, while tumor stages of BRCA are significantly (p < 0.05) associated with the expression of C3, C5, and C5AR1." (PMID 34439277, 2021). "Therefore, targeting C5a or C5aR1 may represent a promising therapeutic strategy for these tumour entities." (PMID 33606748, 2021). "Notably, C5aR1+ neutrophils also promoted BC growth ability in an in vivo tumor model, which could be successfully abolished by WTAP knockdown." (PMID 34312368, 2021). "However, the association between C3, C5, C3AR1, and C5AR1 expression and tumor infiltration of MDSCs and TAMs was not statistically significant and, in most cases, an inverse association was found." (PMID 34439277, 2021).